ENSG00000125695 (novel transcript)
Gene: Protein-coding gene on chromosome 17 (63,702,845 to 63,752,097, reverse strand). Ensembl gene ENSG00000125695.
Genetic constraint (gnomAD): Missense variants: 56 observed, 68.56 expected, observed/expected ratio (o/e) 0.82, 90% interval 0.66 to 1.02. Synonymous variants: 28 observed, 21.98 expected, observed/expected ratio (o/e) 1.27, 90% interval 0.94 to 1.73.